ESR1 (estrogen receptor 1)
Diseases named in the same sentence as ESR1 in open-access papers (continued):
Sharing a sentence is not in itself a finding about the gene and the disease.
breast cancer (continued). "Elacestrant first demonstrated anti-tumor activity in breast cancer patient-derived xenograft (PDX) models, including those harboring ESR1 mutations." (PMID 37019913, 2023). "ESR1 expression levels between DNA and mRNA were compared in 10 breast cancer cell lines to verify that mRNA provides a higher copy number in ER-positive breast cancer." (PMID 37174098, 2023). "Estrogen receptor (ESR1) expression in breast cancer is a good example of a gene, whose expression has both prognostic and treatment defining roles in cancer." (PMID 37146093, 2023). "Similar observations in breast cancer showed tandem duplication of SE regions that activate oncogenes, including ESR1, ZNF217, and MYC." (PMID 37415185, 2023). "Oestrogen receptor alpha (ERα), encoded by the ESR1 gene, is a member of the nuclear hormone receptor superfamily and is expressed in approximately 70% of breast cancer cases." (PMID 37370935, 2023). "Approximately 70–80% of breast cancer patients express high levels of ESR1 in tumor tissue, making it an important target for the treatment of this specific subtype of breast cancer." (PMID 37569854, 2023). "For example, circPVT1 is highly expressed in breast cancer and promotes breast cancer development by targeting both ESR1 mRNA and MAVS protein." (PMID 37723588, 2023). "In patients with breast cancer, 3 (50%) phosphatidylinositol-3-kinase (PI3K) (PIK3CA) actionable mutations were found, and ESR1 actionable mutations were present in 1 (16.67%) patient." (PMID 37371673, 2023). "Taken together, our data indicated that LINC02568 regulates ERα‐target gene activation and ER+ breast cancer cell growth through regulating the expression of ESR1." (PMID 37404090, 2023). "For example, estrogen receptor 1 (ESR1) interacts with the MED1 subunit, which is required for ESR1-mediated transcription and estradiol/ESR1-dependent mammary stem cell function and breast cancer cell growth." (PMID 37607000, 2023). "This challenges the idea that ESR1 downregulation in breast cancer is propelled by selection pressure from endocrine treatment, suggesting that the shift from a hormone-stimulated phenotype serves additional biological purposes." (PMID 38449790, 2023). "The ERα (ESR1 gene) isoform stimulates proliferation and survival of breast tissue and has unequivocally been established as a driver of breast cancer carcinogenesis." (PMID 37711895, 2023). "Comparing samples from cluster B (n = 54) with 63 ER-negative metastatic breast cancer samples, we found that the ESR1 expression itself was higher in samples from cluster B." (PMID 37686693, 2023). "While other EMT-related genes (e.g., SNAI1 and VIM) are highly coexpressed, ESR1 (Estrogen Receptor alpha) is one of the top anticorrelated genes, in agreement with the FOSL1-associated mesenchymal features of triple-negative (and basal-like) breast cancers." (PMID 37176013, 2023). "By targeting the Hippo pathway, VT02956 represses ESR1 expression and inhibits the growth of ER+ breast cancer cells as well as patient-derived tumor organoids." (PMID 37256184, 2023).
breast cancer (continued). "In the molecular classification, “luminal B” breast cancers display a lower expression of ESR1 and a higher expression of proliferation genes." (PMID 37894728, 2023). "Mir-221/222 promotes EMT in breast cancer cell lines through targeting the estrogen receptor (ESR1) and trichorhinophalangeal syndrome type 1 (TRPS1)." (PMID 38002286, 2023). "Collectively, YAP1 acts differently in ER+ breast cancer cells by inhibiting the downstream signaling pathway of the ESR1 gene, which is crucial for ER+ tumor growth." (PMID 37894401, 2023). "In agreement, both miR-18a and miR-18b have been found to be upregulated in canine-mammary-cancer-derived cell lines, and in the sera of dogs with metastatic mammary carcinomas, and also, they have been predicted to target the ESR1 gene." (PMID 36978627, 2023). "In contrast to previous studies on human breast cancer, we observed a higher frequency of PIK3CA mutations in patients with low ESR1 and PGR expression." (PMID 38033642, 2023). "In preclinical studies, the SERCA H3B-6545 had consistent activity against endocrine-therapy-resistant tumors expressing wild-type or mutant ESR1 transcripts, stimulating its testing into an ongoing clinical trial on breast cancer patients (NCT03250676)." (PMID 37760622, 2023). "According to data retrieved from cBioPortal, the expression of ESR1, which encoded ERα, and SERPINA3 were positively related in breast cancer, as evidenced by a Pearson correlation coefficient of 0.47." (PMID 37414914, 2023). "The prevalence of ESR1 in primary mammary tumors is approximately 3%, however, in the metastatic setting, it is 13.6%." (PMID 37371673, 2023). "MiR-4728 affects the efficacy of targeted therapy for HER2-amplified breast cancer by targeting ESR1 and modulating ERα-mediated NOXA transcription to slow apoptosis following treatment with the HER2 inhibitor lapatinib." (PMID 37371458, 2023). "In our results, heterogeneous distribution of the expression of breast cancer-related genes (ESR1, PGR, ERBB2, and MKI67) was observed." (PMID 37759508, 2023). "Survival analyses in the present study revealed that loss of RANBP3L, GLYATL-1, ESR1, and SFXN2 was significantly related to lower RFS in breast cancer (p-value < 0.012, 1.1 × 10−6, 1 × 10−16, and 1.3 × 10−10, respectively)." (PMID 36672708, 2023). "Comparative gene expression profiling and whole-exome sequencing studies between canine and human breast cancers revealed similarities such as cell cycle activation, WNT–β-Catenin signaling, PI3K–AKT and ERK signaling and mutations in ESR1 and BRCA230." (PMID 37009802, 2023). "While progesterone has shown promise in modulating the efficacy of endocrine therapies such as tamoxifen, fulvestrant, and giredestrant against ESR1-mutant breast cancer, the outcomes of such treatments have also been pro-tumorigenic." (PMID 37395734, 2023). "In estrogen receptor-positive (ER+) breast cancer, ChIP-seq shows estrogen receptor (ERα) enrichment at gained SEs in breast cancer over normal breast, including at the ESR1 SE itself which encodes ERα in an autoloop characteristic of SEs." (PMID 37415185, 2023). "PRLR, encoding the receptor for prolactin (which is also called luteotropin, and has been described as the third hormone in breast cancer) resembles ESR1 more than PGR in our study." (PMID 37789381, 2023). "We also anticipate that an increase in SFRP1 expression in breast cancer cell lines should decrease cell viability and reduce ESR1 expression, at least in luminal breast cancer cell lines." (PMID 37190179, 2023). "Single nucleotide polymorphisms (SNPs) in the ERα gene, also known as ESR1, have been implicated as significant factors associated with variations in the risk of developing breast cancer." (PMID 37808197, 2023). "In summary, the detection of ctDNA and ESR1 alterations in ctDNA can provide valuable information on tumor burden and resistance to hormonal treatments in patients with advanced breast cancer." (PMID 37176102, 2023).
breast cancer (continued). "In TCGA breast cancer samples, we observed that ESR1 correlated positively with RKIP (ρ = 0.11), but negatively with BACH1 (ρ = −0.29)." (PMID 37963558, 2023). "Both techniques support the screening and clinical validity of genomic alterations in ctDNA as a ‘liquid biopsy’ in breast cancer, including ESR1 mutants." (PMID 37675216, 2023). "This is poised to change with the development of lines such as the activated ESR1 mice that can be interbred with other GEMs, which should allow for the development of ER positive mouse models of breast cancer." (PMID 37269418, 2023). "This study presents a mechanism involving the DSCAM-AS1/miR-130a/ESR1 genomic axis through which progesterone impedes breast cancer cell invasion and migration." (PMID 36578092, 2022). "The other genetic alteration is served by ESR1 gene fusion, which is enriched in ER+ breast cancer cases and deemed a novel driver of resistance." (PMID 35764927, 2022). "The interaction of FOXA1 with co-factors such as ESR1 and E2F1 enhanced the susceptibility of breast cancer." (PMID 36292640, 2022). "Note the combined enrichment for FOXA1, ESR1, and GATA3 TFs close to the emCpGs; these 3 TFs have already been associated with DNA methylation patterns in estrogen receptor positive breast cancers." (PMID 35440061, 2022). "Early studies on the role of aberrant DNA methylation in breast cancer focused on increased DNA methylation (DNA hyper-methylation) of CpG islands of key cancer genes, including ESR1 and BRCA1." (PMID 35158742, 2022). "Nevertheless, our data suggest the enhanced immune activation in ESR1 mutant breast cancers as a therapeutic vulnerability." (PMID 35440136, 2022). "In breast cancer, CD63+ cancer-associated fibroblast-derived miR-22 promoted tamoxifen resistance via targeting PTEN and estrogen receptor 1 (ESR1)." (PMID 35592419, 2022). "Although Li and colleagues conducted limited functional studies, overexpression of ESR1-e6>YAP1 in ER+ breast cancer cells conferred estradiol-independent growth in their study." (PMID 36686845, 2022). "We provide evidence to support BCK as emerging biomarkers of ESR1 mutant breast cancer and its prognosis, yet their direct functional impact remains ambiguous." (PMID 35440136, 2022). "Our data challenge this overly simplistic model, as LATS1/2 deletion inhibits ER+ breast cancer cell growth due to ESR1 transcriptional repression." (PMID 35217640, 2022). "We initially attempted to understand the mechanisms underlying breast cancer by identifying the high-throughput dataset of ESR1 knockdown breast cancer samples." (PMID 36326669, 2022). "Here the authors reveal that the transcriptional repression of ESR1 is via LATS-YAP-TEAD-VGLL3 axis and the epigenetic regulation of ESR1 super enhancer in ER + breast cancer." (PMID 35217640, 2022). "Several samples had missing or ambiguous status for the two main prognostic and treatment‐predictive biomarkers in breast cancer: oestrogen receptor alpha (ER, gene symbol ESR1) and Erb‐B2 receptor tyrosine kinase 2 (HER2, gene symbol ERBB2)." (PMID 35182081, 2022). "The results showed that CXCL12, ESR1, IGF1, and FOS were significantly associated with the survival of breast cancer." (PMID 35463082, 2022). "Similar to observations in cell lines, ESR1 mutant metastatic breast cancers showed a significant enrichment of basal gene signatures compared to tumors with WT ESR1." (PMID 35440136, 2022). "ESR1 methylation was proposed as mechanism for endocrine resistance in metastatic breast cancer patients." (PMID 35628441, 2022).
breast cancer (continued). "We used reporter gene assays to measure transcriptional antagonistic potencies of antiestrogens in breast cancer cells harboring WT, Y537S, or D538G ESR1." (PMID 35575456, 2022). "Initially, we attempted to elucidate mechanisms underlying breast cancer development by identifying the high-throughput dataset of ESR1-knockdown breast cancer tissue samples." (PMID 36326669, 2022). "Even though the Kaplan–Meier survival analysis of ESR1 in breast cancer showed a reduction in patient survival with increased expression, the result was not statistically significant." (PMID 35273218, 2022). "Overexpression of the ESR1 gene potentially reduces the sensitivity of breast cancer cells to endocrine therapies, leading to disease progression and metastasis." (PMID 36430510, 2022). "Progesterone downregulates the expression of DSCAM-AS1, a known ncRNA member of the ER signaling pathway, and increases the expression of miR-130a that inhibits ESR1, to suppress breast cancer cell invasion and migration." (PMID 36578092, 2022). "Again, the 11-gene signature was more highly expressed in primary breast cancer cases with mutant ESR1." (PMID 36198774, 2022). "Type I collagen-dense ECM can drive the metastases of estrogen receptor 1 (ERα+) breast cancers by altering hormonal signals." (PMID 35008401, 2022). "Recently, single nucleotide polymorphisms (SNPs) in low-penetrance genes, such as ESR1, TOX3, and FGFR2, have been shown to modify the risk of developing breast cancer in a large series of 413 Italian MBCs." (PMID 35454911, 2022). "High expression of these genes was associated with better survival in POG570 metastatic and Dahlgren WT ESR1 primary breast cancer patients." (PMID 36198774, 2022). "Consistent with our findings, a recent study showed that LATS1/2 maintained ESR1 expression and ER+ breast cancer growth by inhibiting YAP/TAZ40." (PMID 35654829, 2022). "Our analyses revealed that ESR2 transcripts are generally much less abundant than ESR1 across all breast cancers." (PMID 35304506, 2022). "The authors conclude that if their results are replicated, ESR1 screening should be considered in ER-positive primary breast cancer." (PMID 35959983, 2022). "SMAD4, of which targets are enriched in FIR20 cells, is essential to inhibit ESR1 transcription in breast cancer cell lines." (PMID 35579852, 2022). "We knocked down GATA3 in the human luminal breast cancer cell line, T47D, and again found that the expression of genes associated with luminal differentiation, such as CDH1 and ESR1, was significantly downregulated." (PMID 34976209, 2022). "Some research showed that activation of ESR1 promotes the growth of breast cancer by triggering downstream signaling pathways, such as MAPK and PI3K." (PMID 35686089, 2022). "We next interrogated the union of the five basal gene sets (N = 742) to identify which basal marker genes were consistently induced in ESR1 mutant breast cancer cells." (PMID 35440136, 2022).
breast cancer (continued). "Although a number of therapeutics with improved efficacy against ESR1 mutant breast cancer are being developed, to our knowledge, OTX015 is the only drug with preferential activity against the Y537S mutant breast cancer cells." (PMID 35881485, 2022). "The current study initially analysed the relationship between ESR1 knockdown models and breast cancer pathogenesis at a systematic level." (PMID 36326669, 2022). "Nevertheless, while a number of therapeutics with improved efficacy against ESR1 mutant breast cancer are being developed, to our knowledge, drugs with preferential activity against the Y537S mutant tumors have not been described." (PMID 35881485, 2022). "Loss of either ARID1A or BRG1 SWI/SNF subunits is frequently observed in diseases in which PGR expression is lost, including breast cancer, in which ARID1A is mutated in 5% of cases and ARID1A and BRG1 are known to play a role in response to ESR1 antagonists." (PMID 35326450, 2022). "Immune context analyses in clinical specimens reveal potential therapeutic vulnerabilities accompanying the increased basal-ness in ESR1 mutant breast cancer, a finding of potential clinical relevance." (PMID 35440136, 2022). "Remarkably, high levels of ESR1-LBD were identified in 16/17 of metaplastic breast cancers which is one of the most aggressive and chemo-resistant subtypes." (PMID 35999225, 2022). "Competitive antiestrogens with selective estrogen receptor degrader/downregulator (SERD) activities with improved potencies show superior therapeutic antagonistic activities compared to 4OHT in breast cancer cells harboring Y537S or D538G ESR1." (PMID 35575456, 2022). "Studies have found that in addition to ESR1 and CYP19A1 gene mutations, 21.5% of AIs drug-resistant breast cancer patients have abnormal amplification of CYP19A1 gene." (PMID 35657638, 2022). "ΔCCDC170, identified in Luminal B breast cancer and generated by ESR1-e2>CCDC170 led to enhanced growth and reduced sensitivity to ET in MBC." (PMID 36686845, 2022). "From the gene enrichment analysis we found that ESR1 was significantly enriched in metastatic relative to primary breast cancer." (PMID 36497297, 2022). "Even though the Kaplan–Meier survival analysis of ESR1 in breast cancer showed a reduction in patient survival with increased expression, the result was not statistically significant (logrank P = 0.1)." (PMID 35273218, 2022). "CTCF has been reported to repress oestrogen-induced gene transcription by hampering ESR1 chromatin binding and enhancer-promoter interaction in breast cancer cells." (PMID 36199058, 2022). "Breast cancer patients had a higher level of E2 and ESR1 mediated activity, which promotes cell proliferation and suppresses apoptosis by directly modulating the genes transcription." (PMID 35386216, 2022). "In independent data sets including n = 4507 ER+/HER2− breast cancers, we found that cancers in patients 50 or younger have lower expression of ESR1 and ER-related genes and higher expression of immune related genes." (PMID 36344517, 2022). "Based on this work, we examined the contribution of SERD activity to the potency and efficacy of transcriptional suppression by antiestrogens in breast cancer cells harboring Y537S or D538G ESR1." (PMID 35575456, 2022). "The AUC of other breast cancer makers are as follows: ESR1 0.572 (p value 3.8 × 10−3), PGR 0.7 (p value 8.6 × 10−5), BCL2 0.577 (p value 1.3 × 10−3), SCUBE2 0.609 (p value 1.5 × 10−5)." (PMID 37304463, 2022). "DNA methylation can upregulate or downregulate ESR1 expression in the in vitro and in vivo breast cancer models." (PMID 35453496, 2022).